PGR (progesterone receptor)
Diseases named in the same sentence as PGR in open-access papers (continued):
Sharing a sentence is not in itself a finding about the gene and the disease.
tumor (continued). "However, we identified a small triple positive (ERBB2 + /ESR1 + /PGR + (HER2 + /ER + /PR +)) DCIS region located in proximity to adipocytes which consisted of a predominantly DCIS #2 tumor epithelium without a KRT15+ myoepithelial cell layer." (PMID 38114474, 2023). "However, it was not related to age, tumor size, histological grade, estrogen receptor, progesterone receptor, HER-2, or Ki67." (PMID 35094653, 2022). "We investigated the efficacy of trastuzumab and pertuzumab in relation to the ER and PgR status of tumours and found a pCR rate of 64.3% (95%CI: 39–89%) in ER-positive and PgR-negative tumours compared to 31.6% (95%CI: 11–52.5%) for ER-positive and PgR-positive tumours." (PMID 35833190, 2022). "Ep4, which was derived from a P51 tumor pathologically assigned to the luminal type because of their weakly positive progesterone receptor (PR) without ER expression (Allred scores: ER, 0; PR, 3), had low VIM activity but the high activity of EGFR and relatively low activity of luminal keratins." (PMID 35676392, 2022). "Besides, PGAM1 has no obvious correlation with the clinical pathological characteristics of patients including age; lymph node (LN) metastasis; tumor‐necrosis‐metastasis (TNM) stage; and estrogen receptor (ER), progesterone receptor (PR), and human epidermal growth factor receptor 2 (HER2) statuses." (PMID 35674458, 2022). "There was no significant between-group difference in tumour biology, including grade (P = 0.303), size (P = 0.916), lymph node status (P = 0.130), oestrogen receptor positivity (P = 0.957), progesterone receptor positivity (P = 0.278), and HER2 receptor positivity (P = 0.959)." (PMID 35674701, 2022). "The increased expression of IL-6 and IL-8 in patients without progesterone receptor expression in tumor G3 usually indicates a poor prognosis, and there is a correlation between IL-8 and neovascularization, which may promote metastatic spread." (PMID 36531035, 2022). "However, unlike PAQR5, PGR and PGRMC1 downregulation were not consistently associated with tumor progression in TNM categories, lymph node invasion, and distal metastasis." (PMID 34572596, 2021). "The tumor cells were negative for estrogen receptor (ER), progesterone receptor (PgR), and HER2." (PMID 33433770, 2021). "The likelihood of BCS + RT decreased if patients were diagnosed during 2000–2004, detected symptomatically, had tumour sizes ≥ 20–≤50 mm, negative/unknown oestrogen and progesterone receptor status, unknown grade and with increasing lymph node involvement." (PMID 33800387, 2021). "Additionally, according to univariate logistic regression, a tumour diameter larger than 2 cm, and the lack of ER and PgR expression were strong influences on high pre-treatment heparanase in IBrC patients." (PMID 34070058, 2021). "O6-methylguanine-DNA methyl-transferase (MGMT) and progesterone receptor (PgR) expression could not be assessed, due to insufficient tumor materials." (PMID 33967965, 2021). "Interestingly, tumor secretion of CCL22 was found to be positively correlated with intratumor Treg infiltration and with aggressive tumor features such as high histological grade, lack of ER and PgR expression, and HER2 amplification." (PMID 34944971, 2021). "The results revealed that a p140Cap positive status was associated with negative lymph node status, ER and progesterone receptor (PgR)-positive status, small tumor size, low grade, low Ki67 status, and correlates with a better prognosis in ERBB2-positive patients." (PMID 34708040, 2021). "We found that neither tumor size nor nodal involvement, stage of the disease, tumor grade, Ki67 level, and progesterone receptor status could individually predict the response to such treatment." (PMID 33939116, 2021).
tumor (continued). "Compared with women with high THRα-2 tumor expression, women with low THRα-2 tumor expression were more likely to have ER- and PgR negative tumors, HER2-positive tumors, higher Ki67 and histological grade, as well as larger tumors, and were more likely to have ALNI." (PMID 34930399, 2021). "Tumor has moderate PgR expression with negative ER immunostaining and a labeling index up to 15%." (PMID 33981288, 2021). "Notably, canonical breast cell differentiation genes and molecular markers (KRT8, KRT18, KRT14, TP63, ERBB2, ESR1, PGR) were not differentially expressed, suggesting the cells maintain their differentiation state and tumor subtype." (PMID 34741115, 2021). "BLBCs are similar and are often used to indicate another group of neoplasms, namely triple-negative breast cancers (TNBCs), which are characterized by the lack of expression of the estrogen receptor (ER), progesterone receptor (PR), and the human epidermal growth factor receptor 2 (Her2/neu)." (PMID 33080870, 2020). "Consequently, the F2P Score was established based on the combination of six genomic variables (ESR1, PGR, CD68, BAG1, BCL2, and GSTM1) and two clinicopathological variables (age and categorical tumor size) with the shrinkage factors of 0.314 and 0.888, respectively." (PMID 33042787, 2020). "In each tumor type, FUT8 expression showed significant (p< 0.05) correlation with one or more clinicopathological parameters; these included patient gender, molecular subgroup, histological grade, TNM stage, estrogen receptor, progesterone receptor, and recurrence status." (PMID 33323540, 2020). "In addition, the tumor may also be positive for Vimentin, α-inhibin, SMA, estrogen receptor and progesterone receptor." (PMID 33292402, 2020). "In this study, RYNXC could significantly decrease ESR1, PGR, EGFR, PTGS2, and Src mRNA expressions in a dose-dependent manner in MCF-10AT cells or breast precancerous lesion model rats, which could further inhibit cell proliferation and tumor progression." (PMID 30906412, 2019). "Additionally, the tumor was estrogen receptor (RE) positive in 10% of the cells, progesterone receptor (PgR) negative, and Her2-neu negative (1+)." (PMID 31651866, 2019). "As previously reported, in our cohort FOXA1 positivity was associated with small tumor size (< 15 mm), absence of lymph node metastases, low histological grade, no special type (NST) histotype, low level of Ki67, as well as, with ER+ and PgR+ tumors." (PMID 29970021, 2018). "Due to the fact that these triple negative (ERα-/PgR-/Her-2) cancer cells are considered to be very aggressive and since some commonly used chemotherapeutics like Herceptin (HER-2 targeting) lack activity on these kinds of cells, alternative approaches are necessary to affect such tumor types." (PMID 30423956, 2018). "Tumor subtypes were defined according to the expression of ER, progesterone receptor (PgR), and human epidermal growth factor receptor 2 (HER2); luminal (ER+ and/or PgR+, HER2-), luminal-HER2 (ER+ and/or PgR+, HER2+), HER2-enriched (ER- and PgR-, HER2+), and triple-negative (ER-, PgR- and HER2-)." (PMID 30093965, 2018). "The tumor was estrogen receptor-positive and progesterone receptor-negative." (PMID 29707112, 2018). "Similarly, high expression of SLC7A5 mRNA was significantly associated with hormone receptor negative (ER- and PgR-) and HER2+ tumours (all p < 0.001)." (PMID 29566741, 2018). "High expression of PD-L1 is associated with poor-prognosis characterized by progesterone receptor (PR)-negative, estrogen receptor (ER)-negative, and human epidermal growth factor receptor 2 (HER2)-positive status, large tumor size, and high proliferation and grade." (PMID 29245948, 2017).
tumor (continued). "To determine, in this data set, if our prognostic score was independent of age at diagnosis, tumor grade, estrogen- and progesterone-receptor status and molecular subtype (PAM50) we ran multivariate Cox regression force-entry with these factors including the prognostics scores as covariates." (PMID 28122328, 2017). "The tumor was negative for estrogen receptor (ER), progesterone receptor (PgR), and HER2/neu." (PMID 28233285, 2017). "The pooled results showed that TILs were associated with clinicopathological parameters of biologically aggressive phenotypes, such as high tumor grade or estrogen/progesterone receptor negativity, but they were not correlated with human epidermal growth factor receptor-2 expression." (PMID 27329588, 2016). "We did not observe any association between: progesterone receptor status, HER2 expression and tumor grade described by Bloom-Richardson grading system, and the distribution of genotypes and frequency of alleles for these polymorphisms of the SENP1 and SENP2 genes (data not shown)." (PMID 27178176, 2016). "Immunohistochemical analysis showed that the primary tumor exhibited two different histological features including triple‐negative components at lesion 1 (ER− PgR− HER2−) and hormone receptor positivity at lesion 2 (ER+ PgR+ HER2−); and all three metastasis sites were ER+ PgR+ HER2−." (PMID 27774772, 2016). "In our study, elevated levels of HER2/ECD correlated positively with parameters related to tumor aggressiveness, such as vascular invasion, metastatic status, or negativity of estrogen receptors, but not with invaded lymph nodes and progesterone receptor-negative tumors." (PMID 27709352, 2016). "However, in present day routine diagnostics, intratumoral heterogeneity of PgR expression is not reported, which contrasts with the present reporting of Ki67 in “hot spot” regions of the tumor." (PMID 26970778, 2016). "Ten articles contained information of the impact of MMP-2 expression on tumor sizes, nine on lymph nodes status, two on distant metastasis, eight on TNM stage, nine on histological grade, ten on estrogen receptor status and nine on progesterone receptor status." (PMID 25816052, 2015). "There was no expression of HapPar-1, CD10, CD56, or progesterone receptor (PR) in tumor cells." (PMID 25886790, 2015). "In univariate analysis using continuous clinicopathological biomarkers, high CIN25 and CIN70 scores were associated with younger age (p < 0.0001), high tumour grade (p < 0.0001), PgR negativity (p < 0.0001) and ER negativity (p < 0.0001) but not with tumour size, nodal status or HER2 status." (PMID 26372731, 2015). "Therefore, the existence of ER-/PgR+ tumours remains controversial and ER-/PgR+ tumours are not classified into any of the subtypes according to the 2013 St Gallen guidelines." (PMID 25938238, 2015). "However, some reports have shown that PgR expression is not correlated with the LN status or tumour size, which is inconsistent with our results." (PMID 25938238, 2015). "When we restricted our analyses to breast cancer tumors that were either estrogen-receptor or progesterone-receptor positive (ER+/PR+), the overall pattern of estimated risks was generally similar to those observed for all tumor types considered in our original analysis (data not shown)." (PMID 25636809, 2015). "Compared with ER-/PgR- patients, those with ER-/PgR+ tumours were non-significantly younger at the time of diagnosis (median age 50 versus 59 years, p = 0.28), were less likely to be high grade (50.0% vs 75.7%, p = 0.001) and had smaller median tumor sizes (1.85cm vs. 2.5cm, p = 0.01)." (PMID 26161666, 2015).
tumor (continued). "In addition, young age, early year of diagnosis, large tumor size, LN involvement, negative ER and PgR status, incomplete radiotherapy, and the inner and lower primary tumor sites were independently associated with increased BCSM (P<0.0001)." (PMID 24740002, 2014). "In our case, the tumor was positive for the ER, and negative for the PgR and HER2." (PMID 24708742, 2014). "This has been reported in the literature where others have demonstrated better outcome of basal like tumours as compared to pure triple negative/quadruple negative (Quadruple negatives defined as the tumours negative for ER, PgR, HER2 and CK5/6 expression) tumours." (PMID 24999743, 2014). "Moreover, miR-10b was significantly underexpressed in estrogen/progesterone receptor (ER/PR) negative tumors relative to ER/PR positive tumor tissues." (PMID 25232827, 2014). "It should be noted that our cohort is entirely Han Chinese in origin (compared to those based on Caucasian populations), the majority of patients are aged below 55 years (68%) and the cohort contains a predominance of ER- (59%) and progesterone receptor negative (PR-) (56%) tumours." (PMID 25266665, 2014). "Additional pre-operative variables associated with higher utilization rates of NAC included known positive nodal status (P<0.0001), increasing tumor size (P<0.0001), negative estrogen receptor (ER) status (P<0.0001), and negative progesterone receptor (PR) status (P<0.0001)." (PMID 24376822, 2013). "The tumor cells stained negative for mesothelial cell markers (D2-40 and calretinin), but positive for the Wilms' tumor-1 (WT-1) antibody, the estrogen receptor (ER) and the progesterone receptor (PR) in the immunohistochemical stains." (PMID 23420814, 2013). "High S6K2 and/or 4EBP1 was primarily seen in ER/PgR-negative tumours in the van de Vijver and Uppsala cohorts and the same tendency could be seen in the Karolinska cohort." (PMID 24131622, 2013). "The tumour was oestrogen and progesterone receptor negative." (PMID 23097739, 2012). "The presence of the progesterone receptor (PR) increases the likelihood of hormone responsiveness, while progesterone receptor-negative tumours are less responsive to therapy, perhaps suggesting that PR may be necessary for adequate therapeutic outcome." (PMID 22973310, 2012). "Therefore we conclude that regulation of signaling pathways in patient samples can not only be attributed to the presence or absence of tumor infiltrating lymphocytes, but also to changes in progesterone receptor signaling." (PMID 22295114, 2012). "In fact, recent recommendations suggest that ER and PgR assays be considered positive, for therapeutic purposes, if there are at least 1% positive tumour nuclei, but these data were not available for the majority of carriers in our samples to enable reclassification." (PMID 22053997, 2011). "Thus, the tumours of younger women were more frequently estrogen receptor (ER)/progesterone receptor (PgR)-negative (χ2 = 7.07; P = .008), HER2 amplified (χ2 = 5.76; P = .01), and with high (≥10%) Ki67 labelling index (χ2 = 9.53; P = .002)." (PMID 22332011, 2011). "Snai1 was inversely associated with a positive estrogen receptor status (p = 0.041), but not with the progesterone receptor (p = 0.58) nor with the size of the tumor (p = 0.301), presence of metastases (p = 0.57), grade of tumor (P = 0.10, grade I-II/III) or HER2 amplification (p = 0.215)." (PMID 21324165, 2011). "Although neither estrogen nor progesterone receptor status were significantly associated with RPMM methylation profiles, large numbers of specific CpG loci had significant methylation associations with these tumor characteristics in locus-by-locus analysis." (PMID 20686660, 2010).
tumor (continued). "Furthermore, BRCA1 tumours show a so-called ‘triple negative’ phenotype being oestrogen receptor (ER), progesterone receptor (PgR) and HER2 negative." (PMID 19724277, 2009). "Perhaps in the context of HER2 overexpression and ER positivity, low or absent PgR expression may be a predictor of tumour dependence on HER2 activity and thus sensitivity to HER2 inhibition with agents such as lapatinib." (PMID 19844234, 2009). "The univariate analysis for prognostic factors associated with 5-year overall survival revealed that the tumor group as TNBC or non-TNBC was statistically significant, in addition to age, tumor size, lymph node, metastasis, grade, stage, ER status, and PgR status." (PMID 19534825, 2009). "Progesterone receptor status was not available for four tumours from our cohort of 262 patients." (PMID 19018258, 2008). "Similarly, women with PABC were more likely to have tumours of high histological grade, to exhibit a high level of mitosis, and to be progesterone receptor negative than matched nonpregnant control women." (PMID 18271969, 2008). "Paralleling the odd histologic finding is an additional finding that the tumor is negative for estrogen receptor (ER) expression, negative for progesterone receptor (PR) expression, but strongly positive for human epidermal growth factor receptor 2 (Her-2/neu) overexpression." (PMID 19108734, 2008). "cMyc is amplified in 20–30% of breast tumors and amplification has been correlated with pre-menopausal status, specific tumor features (i.e., high tumor grade, lymph-node metastases, large tumor size and negative progesterone receptor status) and worse prognosis." (PMID 17567920, 2007). "There was a significant interaction with hormone receptor status: women who had ER-positive but PgR-negative tumours were likely to have a superior outcome with anastrozole, whereas women with tumours that were positive for both receptors did just as well with tamoxifen as with anastrozole." (PMID 17892469, 2007). "On the other hand, the in situ tumours were mostly Her-2 negative, and ER and PgR positive." (PMID 17892570, 2007). "One out of four women with ER positive tumour, achieving a pCR, had negative PgR." (PMID 17047649, 2006). "On the other hand, the impressive increase of the pCR rate in ER/PgR negative tumours with the weekly treatment could represent a simple ‘optical illusion’ if not followed by a substantial advantage in long-term disease-free survival of patients." (PMID 17047649, 2006). "The tumor is negative for the estrogen receptor and the progesterone receptor." (PMID 16729884, 2006). "Finally, the tumor is negative for Estrogen receptor, Progesterone receptor, brst-2 antigen, and mammoglobin." (PMID 16729884, 2006). "A key question is whether AIs have substantially better efficacy than tamoxifen for ER-positive–PgR-negative tumours, where the data are currently contradictory." (PMID 16434989, 2006). "The very high levels of progesterone receptor detected in this tumour support the hypothesis that the PCSTP is oestrogen-responsive, since expression of progesterone receptor is induced by oestrogen, and thus constitutes an index of effective oestrogen action in a given tissue." (PMID 16188022, 2005). "The conclusion from the EBCTCG overview in 1998 was that all postmenopausal women with a positive hormonal receptor status should receive hormonal therapy and that there was no clear benefit from tamoxifen in women with oestrogen and progesterone receptor-negative tumours." (PMID 15213715, 2004).